ELN (elastin)
Diseases named in the same sentence as ELN in open-access papers (continued):
Sharing a sentence is not in itself a finding about the gene and the disease.
heart failure (7 papers, 2011 to 2025). Inability of the heart to pump blood at an adequate rate to meet tissue metabolic requirements. "We implanted cells genetically modified to overexpress elastin to re-establish the elastic properties of the infarcted myocardium and prevent cardiac failure." (PMID 22435995, 2012). "Additionally, few studies have evaluated elastin expression and protein content in the heart, and these studies mainly focused on heart failure." (PMID 27069251, 2016). "Additionally, cardiac overexpression of miR-195 results in pathological cardiac growth and heart failure in transgenic mice, so that modulation of miR-15 miRNAs during development and maturation are unlikely to allow specific conclusions about the effect of miR-15 miRNAs on elastin metabolism." (PMID 21305018, 2011). "Consistent with our observations, reported that relative elastin mRNA levels did not significantly differ between Yucatan miniature swine with induced heart failure that exercised versus those that remained sedentary (both healthy control and sedentary with heart failure)." (PMID 27069251, 2016).
Inguinal hernia (6 papers, 2015 to 2023). Protrusion of the contents of the abdominal cavity through the inguinal canal. "Each of these inguinal hernia risk genes has a plausible biological and pathophysiologic role in the development of hernias, which is known to have metabolic aetiology related to collagen subtype and maturation, elastin and matrix metalloproteinases, in addition to congenital and acquired factors." (PMID 26686553, 2015). "In this report, we present a boy with a novel mutation in exon 15 of the ELN gene, who presented with mild SVAS, severe branch pulmonary artery stenosis, and inguinal hernia." (PMID 37980465, 2023). "The anterior rectus sheath of patients with direct inguinal hernias was thinner and had significantly lower collagen and elastin content and a decrease in the ratio of hydroxyproline to proline in patients with an indirect inguinal hernia with controls." (PMID 34976388, 2022). "Decreases in collagen and elastin have also been observed in the rectus sheath and peritoneal cavity of patients with direct and indirect inguinal hernias." (PMID 34976388, 2022). "Pathway analyses identify several genes with a strong link to collagen and/or elastin (ADAMTS6, ADAMTS16, ADAMTSL3, LOX, ELN) in the vicinity of associated loci for inguinal hernia, which substantiates an essential role of connective tissue morphology." (PMID 35680855, 2022). "Our findings suggest a role for the regulation of both collagen homoeostasis and elastin maintenance in the development of inguinal hernias, which appear to also influence anthropomorphic traits, the risk of cancer and lung function." (PMID 26686553, 2015).
lumbar spinal stenosis (6 papers, 2009 to 2025). A spinal stenosis that involves the lumbar region of vertebral column. "Lumbar spinal stenosis (LSS) is a relatively common cause of lower back pain in older adults, and it is characterized by age-associated fibrosis, reduced elastin-to-collagen ratios, and ligamentum flavum (LF) hypertrophy." (PMID 33568575, 2021). "One of the characteristics of lumbar spinal stenosis (LSS) is elastin degradation and fibrosis in the ligamentum flavum (LF)." (PMID 31638980, 2019). "The increased collagen-to-elastin ratio has also been considered as a sign of developing lumbar spinal stenosis in elder patients." (PMID 25022571, 2014). "Change of the ratio of elastin to collagen has been considered as a sign of developing lumbar spinal stenosis in elder patients." (PMID 25022571, 2014). "The current results suggest that the increased expression of active MMPs by the ligamentum flavum fibroblasts might be related to the elastin degradation and fibrosis of the ligamentum flavum in the patients who suffer with lumbar spinal stenosis." (PMID 19885059, 2009). "Ligamentum flavum hypertrophy (LFH) represents a key pathological factor in lumbar spinal stenosis (LSS), which is characterized by abnormal collagen deposition, reduced elastin fibers, and other degenerative changes." (PMID 41394908, 2025). "Lumbar spinal stenosis (LSS) is a condition wherein patients exhibit age-related fibrosis, elastin-to-collagen ratio reductions, and ligamentum flavum hypertrophy." (PMID 33568575, 2021). "It contributes to lumbar spinal stenosis (LSS), including fibrocartilaginous pathological degeneration due to the excessive proliferation of collagen, calcium crystal deposition, collagen and elastin fibre changes, and metaplasia of the ligament fibroblasts." (PMID 36233586, 2022).
renal fibrosis (6 papers, 2015 to 2025). A final common manifestation of a wide variety of chronic kidney diseases characterized by glomerulosclerosis and tubulointerstitial fibrosis. "Dysregulation of the major ECM proteins such as collagen, fibronectin, α-smooth muscle actin (α-SMA), and elastin is the hallmark of renal fibrosis and failure in DN1,4,5." (PMID 36522378, 2022). "Recent advances demonstrate that elastin quantification promotes reproducible assessment of renal fibrosis progression and longitudinal evaluation of antifibrotic therapeutic efficacy." (PMID 40558439, 2025). "Together, this leads to the upregulation of Col IV and fibronectin along with excessive collagen deposition in the glomerular and tubulointerstitial regions, and degradation of vascular elastin resulting to the renal fibrosis." (PMID 36522378, 2022). "LOXL-2 crosslinks collagens and elastin resulting in increased ECM stiffness and has been associated with renal fibrosis and pathology." (PMID 33748219, 2021). "Moreover, our study showed a robust collagen deposition in the glomerular and tubulointerstitial regions and degradation of vascular elastin content resulted to renal fibrosis in diabetic kidney, corroborating our earlier findings." (PMID 36522378, 2022). "In addition, upregulated MMP-9 and MMP-13, excessive collagen deposition in the glomerular and tubulointerstitial regions, and degradation of vascular elastin resulted to renal fibrosis in the Akita mice." (PMID 36522378, 2022).
rheumatoid arthritis (6 papers, 2018 to 2025). A chronic, systemic autoimmune disorder characterized by inflammation in the synovial membranes and articular surfaces. "Sulfasalazine S5, a sulfonamide active in rheumatoid arthritis, ulcerative colitis and Crohn’s disease has an affinity for connective tissues containing elastin." (PMID 40572550, 2025). "We set out to investigate whether the age-associated elastin degradation is enhanced in AAA, bronchiectasis, rheumatoid arthritis (RA) and COPD compared to control subjects." (PMID 38413600, 2024). "Moreover, vitamin K2 supplementation reduced serum MMP-3 levels in subjects with rheumatoid arthritis, which may also support the concept of vitamin K as an inhibitor of elastin degradation." (PMID 36835797, 2023). "Rheumatoid arthritis (RA) is an autoimmune disease, characterized by an irregular immune response towards components of the connective tissue, such as collagen and elastin, also present in the structure of the cornea, and it is associated with higher incidence of bilateral HSV keratitis (40%)." (PMID 35736971, 2022).
acute respiratory distress syndrome (5 papers, 2018 to 2022). Progressive and life-threatening pulmonary distress in the absence of an underlying pulmonary condition, usually following major trauma or surgery. "Flavonoids such as kaempferol, myricetin, and quercetin could block elastase enzymes, which are produced by neutrophils and can enhance elastin and fibronectin, leading to many diseases such as pulmonary emphysema, respiratory distress syndrome, and acute respiratory distress syndrome (ARDS)." (PMID 35566252, 2022).
Aortic root aneurysm (5 papers, 2020 to 2024). An abnormal localized widening (dilatation) of the aortic root. "In MFS, an aortic root aneurysm is associated with aortic wall medial elastin fragmentation." (PMID 39684412, 2024). "On histologic analysis, percent area of elastin, collagen and smooth muscle cells were greater in aortic root aneurysms." (PMID 38204645, 2023). "The most significant additional findings found in the ascending aorta and aortic root aneurysm specimens, were the presence of high-density collagen fibers and lack of elastin fibers on observation." (PMID 34496896, 2021).
Autoimmunity (5 papers, 2012 to 2025). The occurrence of an immune reaction against the organism's own cells or tissues. "Surely this model is not good for the direct study of epithelial injury since it is conceived on the basis of elastin-mediated autoimmunity in COPD pathogenesis." (PMID 33828547, 2021). "We have recently developed a new COPD mouse model based on the CS-initiated and elastin-driven autoimmunity." (PMID 33828547, 2021). "While many genetic factors shape individual responses to environmental insults such as cigarette smoke, our findings here point to the need to define the genetic basis of elastin autoimmunity induced by exposure to cigarette smoke." (PMID 22969766, 2012). "In addition to humoral autoimmunity, autoreactive T cells, particularly those targeting elastin, an extracellular protein crucial for lung integrity, have been implicated in contributing to the development of COPD and its animal model." (PMID 39975554, 2025). "Finally we identified smokers that harbor anti-elastin autoimmunity with confirmatory cloning and characterization of CD4 T cells using specific major histocompatibility cluster II (MHC-II) tetramers." (PMID 22969766, 2012).
congenital heart disease (5 papers, 2016 to 2026). A heart disease that is present at birth. "Here we report of an ELN heterozygous variant associated with congenital heart disease accompanied with pulmonary artery stenosis, which is less common." (PMID 34238994, 2021). "Besides congenital heart diseases, elastin gene knockout leads to diffuse arteriopathy: specific lesions imply a thickening of supra-aortic trunks and renovascular involvement." (PMID 27069694, 2016).
exfoliation syndrome (5 papers, 2019 to 2024). An autosomal dominant disorder caused by mutations in the LOXL1 gene, encoding lysyl oxidase homolog 1. "In Pseudoexfoliation Glaucoma, the deficiency of Loxl1 is associated with decreased elastin incorporation into elastic lamina of blood vessels, resulting in released soluble elastin and leakage of serum proteins, inflammatory cytokines into aqueous humor." (PMID 34923484, 2021). "For example, a large-scale GWAS study found that LOXL1 variants can increase the deposition of elastin and fibrillin-1 that stabilizes the ECM, thereby protecting against exfoliation syndrome." (PMID 34393991, 2021).
glioma (5 papers, 2021 to 2024). A benign or malignant brain and spinal cord tumor that arises from glial cells (astrocytes, oligodendrocytes, ependymal cells). "Accordingly, we found that FHOD1 knockdown significantly increased elastin‐induced ferroptosis in glioma cells T98G and U251." (PMID 37211949, 2023). "Our Kaplan–Meier analysis demonstrated that high expression of COL1A1, COL1A2, COL3A1, COL5A1, COL8A1, ELN, FN1 resulted in lower OS in all grade glioma patients, in turn causing poor prognosis." (PMID 36106447, 2022). "Analysis of the associative relationships ofindividual representatives of the selected pairs revealed that the level ofmRNAs encoded by the ELN, ARL4C,C9orf64, PLAT, and FKBP9genes associated with aggressive progression of glioma was increasedin the IDHwt group." (PMID 39539523, 2024). "Therefore, the effect of Neu2 on the amount of elastin in the skin was examined by using rat Neu2 expressed in C6 rat glioma cells." (PMID 33558588, 2021).
hepatocellular carcinoma (5 papers, 2016 to 2024). A malignant tumor that arises from hepatocytes. "Recent studies reveal that elevated elastin and collagen fiber accumulation correlates with increased incidence and poorer prognosis in cancers such as hepatocellular carcinoma and gastric cancer." (PMID 39770505, 2024). "In many types of cancer, such as liver cell carcinoma, the elastin content is a major factor." (PMID 34827210, 2021). "Exposure of hepatocellular carcinoma cells (HCC) to ferroptosis-inducing compounds, such as elastin and sorafenib, promotes the nuclear accumulation of Nrf2 through the inactivation of KEAP1 by p62 expression." (PMID 35163335, 2022). "The fibrosis stage, which is evaluated by the distribution pattern of collagen fibers, is a major predictor for the development of hepatocellular carcinoma (HCC) for patients with hepatitis C. Meanwhile, the role of elastin fibers has not yet been elucidated." (PMID 27128435, 2016).
Hernia (5 papers, 2010 to 2025). "Patients with Ehlers–Danlos syndrome or cutis laxa, which feature mutations in collagen or elastin genes, display high rates of abdominal-wall defects, underscoring that localized hernia may represent a milder phenotype of generalized ECM fragility." (PMID 41440470, 2025). "LOXL1—an elastin/collagen cross-linking enzyme—shows reduced expression in direct hernia fascia together with increased elastase, implying impaired elastic-fiber integrity and suboptimal cross-link maturation within the load path of the groin." (PMID 41440470, 2025). "A multi-cohort analysis identified susceptibility loci near ELN, FBLN5, and LOX, genes that govern elastic-fiber assembly and collagen cross-linking, confirming that hernia risk aggregates with loci mediating ECM homeostasis." (PMID 41440470, 2025). "Beyond collagen, elastin integrity is impaired in hernia patients." (PMID 41440470, 2025). "In hernia-prone fascia specifically, LOXL1 (a cross-linking enzyme essential for both elastin and collagen maturation) is downregulated, while elastase activity is elevated, a signature of impaired elastic-fiber repair and inferior cross-link maturation within the transversalis fascia load path." (PMID 41440470, 2025). "Additionally, Surgisis is predominantley composed of collagen rather than elastin compared to dermal-based biomaterials; thus it is expected to result in less abdominal diathesis or hernia recurrence overtime." (PMID 20727181, 2010).
hyperhomocysteinemia (5 papers, 2017 to 2025). A serious metabolic condition caused by mutations in the MTHFR gene, medications, or nutritional deficiency. "Specifically, degradation of elastin, proliferation of vascular smooth muscles, increased collagen synthesis, activation of calcification and fibrosis, deficient nitric oxide formation, increased reactive species generation and endothelial damage, were associated with hyperhomocysteinemia." (PMID 32735567, 2020). "Alterations in elastin content and structure have been reported previously in several different animal models of hyperhomocysteinemia." (PMID 28414812, 2017). "Firstly, hyperhomocysteinemia may disrupt the structural integrity of elastin, collagen and proteoglycans, leading to decreased muscle strength." (PMID 38808112, 2024).
intracranial aneurysms (5 papers, 2012 to 2024). "Although the genetic analysis of DH is limited, the presence of a specific variant of the ELN gene has been found to indicate a heightened vulnerability among to the development of intracranial aneurysms in individuals of East Asian descent." (PMID 39457566, 2024). "Both aortic and intracranial aneurysms share the characteristic feature of vascular wall degradation, particularly involving the loss of elastin and the apoptosis of SMCs." (PMID 39595942, 2024). "For example, several genetic association studies have linked elastin with the development of intracranial aneurysms (IA) as well as increased risk of isolated systolic hypertension and age-related alterations in carotid artery distensibility." (PMID 23049958, 2012). "Evidence from a case-control study indicated that the elastin gene polymorphism might be associated with the formation and the rupture of intracranial aneurysms." (PMID 26830841, 2016).
psoriasis (5 papers, 2011 to 2024). An autoimmune condition characterized by red, well-delineated plaques with silvery scales that are usually on the extensor surfaces and scalp. "The systemic pro-inflammatory state accompanying aging and psoriasis induces elastin remodelling in arteries, and elastin degradation products can stimulate elastogenesis and pathological neoangiogenesis." (PMID 35625870, 2022). "The expression of elastin gene can be enhanced by various factors increased in both psoriasis and during aging, including TGF-β, TNF-α, and elastin fragments." (PMID 35625870, 2022). "Our analysis indicates that the levels of native elastin might strongly reflect both the severity of psoriasis and the aging process." (PMID 35625870, 2022). "The discovery of the relationships between the levels of native elastin, aging, and the severity of psoriasis is a novelty with promising potential for clinical practice, but further research is needed to confirm the observed relationships in larger groups of geriatric and psoriatic patients." (PMID 35625870, 2022). "However, the elastin levels, the age, and the severity of psoriasis (PASI) all significantly correlated with each other among the participants." (PMID 35625870, 2022). "We do not know whether trappin-2 is also specifically conjugated to elastin in vivo, although there is evidence that it can be detected as high-molecular weight forms in psoriasis skin or lung tissues, as a probable consequence of tranglutaminase-mediated conjugation." (PMID 21687692, 2011). "Our results might imply that compensatory or pathological elastogenesis is less stimulated, dysregulated, or insufficient in psoriatic patients with more severe psoriasis, despite increased TGF-β1 expression, which promotes elastin expression." (PMID 35625870, 2022). "The role of elastin in psoriasis has not been specified either." (PMID 38693919, 2024).
type 2 diabetes (5 papers, 2020 to 2023). "In contrast, a reduction in the elastin in the adipose tissue has been associated with glucose uptake interference, and the induction of IR and type 2 diabetes." (PMID 36499567, 2022). "Moreover, in a previous experiment involving rats with type-2 diabetes, a decrease in elastin levels was associated with a decrease in skin stiffness when bulging stress was applied." (PMID 37072855, 2023).
viral infection (5 papers, 2014 to 2023). "Our data highlighted and confirmed that matrix metalloproteinases play key roles in viral infection and progression through airway remodeling (i.e., loss of the epithelium barrier integrity and elastin degradation in the ECM)." (PMID 37569398, 2023). "Neutrophils are known to be part of inflammatory responses that secrete elastin during viral infection." (PMID 35284643, 2022). "Factors including improper uterine posture, a large calf on the heifer, inadequate nutrition, goiter, viral infections, neuromuscular problems, elastin and collagen defects, and mineral imbalance are said to have a significant part in the development of congenital tendon diseases and disorders." (PMID 37155544, 2023). "Indeed, collagen and elastin peptides exert chemotactic effects that draw in inflammatory cells that are needed for the elimination of viral infections in the lung." (PMID 24587397, 2014).